TRPV1 (transient receptor potential cation channel subfamily V member 1)
Diseases named in the same sentence as TRPV1 in open-access papers (continued):
Sharing a sentence is not in itself a finding about the gene and the disease.
tumor (continued). "When mEERL tumors were implanted in a transgenic mouse model that lacks TRPV1+ sensory nerves, tumor growth was significantly attenuated, which confirms that tumorigenesis is sensory nerve neuritogenesis-dependent." (PMID 35455973, 2022). "First, TRPV1 can regulate the flow of calcium ions, thereby reducing the proliferation of tumor cells." (PMID 36304985, 2022). "Though we did not detect a significant change in Trpv1 expression at the whole ganglia level, we did find a significant reduction in Trpv1 relative expression in tongue-innervating TG neurons from MOC2 tumor-bearing male mice compared to male PID14 shams." (PMID 36172037, 2022). "TRPV1 immunolabelling was increased by around twofold in the tumour compared to adjacent healthy tissue in each of the ten biopsies examined." (PMID 36323780, 2022). "An integrated analysis reported that TRPV1 is a novel tumor suppressor and prognosis marker for ccRCC." (PMID 35558077, 2022). "Here, we show that TRPV1, as a tumor suppressor gene, regulates the occurrence and development of CSCC by regulating inflammatory response, ferroptosis, and methylation levels." (PMID 36072430, 2022). "The numbers of tumour-infiltrating lymphocytes (TILs) correlated (R2 = 0.63) with increased TRPV1 immunolabelling." (PMID 36323780, 2022). "Meanwhile TRPV1 is positively correlated with T cells and negatively associated with macrophages, indicating that TRPV is associated with tumor cell immunity." (PMID 36072430, 2022). "Resulted in a large proportion of sensory neurons innervating the tumor-bearing bone expressed TRPV1." (PMID 36438444, 2022). "When assessing the sexes individually, there was a significant increase in the percentage of DiI-positive CGRP-IR neurons (p = 0.032) and TRPV1-IR (p = 0.007) in TG sections from MOC2 tumor-bearing female mice compared to female PID14 sham mice." (PMID 36172037, 2022). "In fact, a previous study has demonstrated that the use of TRPV1 agonists can promote tumor cell proliferation, supporting our findings." (PMID 36304985, 2022). "Compared to the paired adjacent normal tissues, the mRNA expression level of TRPV1 in the tumor tissues of LUAD and LUSC was significantly higher." (PMID 35620019, 2022). "Compared with empty vector group, the tumor weight of TRPV1 overexpression group was reduced and the tumor growth was inhibited." (PMID 35402237, 2022). "TRPV1 stimulation also triggers tumor cell death via the activating transcription factor-3 (ATF3)-controlled branch of the endoplasmic reticulum stress pathway." (PMID 34458247, 2021). "This anti-tumor effect was related to the downregulation of ERα, PRα&β, and TRPV1 expression, maintenance of immune function, especially by preserving NK cell activity, and reduced production of proinflammatory cytokines such as TNF-α and IL-6." (PMID 34764420, 2021). "TRPV1 expression has been reported to be higher in human primary brain tumors than tumor-free brains." (PMID 34131404, 2021). "As both chronic inflammation as well as abnormal calcium signaling play a role in tumorigenesis, it seems plausible that TRPV1 is involved in tumor progression." (PMID 34199609, 2021). "From the current clinical and experimental data, it is likely that TRPV1 serves as a repressor of metastasis, which is in line with its tumor-suppressing role." (PMID 34131404, 2021). "Expression of TRPV1 decreases progressively as tumor stage increases, and receptor expression possibly correlates to cell differentiation." (PMID 33477303, 2021). "The results of our current study indicated that TRPV1 acted as a tumor suppressor gene in ccRCC according to discoveries from the following 4 aspects." (PMID 32913462, 2020).
tumor (continued). "Spinal cord NLRP1 inflammasome-mediated inflammatory response contributes to dry skin-induced chronic itch by TRPV1 channel, and it is also involved in age and sex differences of chronic itch." (PMID 32312281, 2020). "We also conducted another survival analysis between TRPV1 expression and cumulative survival in each tumor immune subset." (PMID 32913462, 2020). "Due to tumor heterogeneity and complexity, the comprehensive role of TRPV1 in affecting ccRCC survival requires additional research to elucidate the details." (PMID 32913462, 2020). "Western blot analysis showed significant upregulation of TRPV1 level in DRG tissues ipsilateral to the tumor-bearing bone from PTDs 14 to 28 (1-way ANOVA, F = 3.83, P = 0.02)." (PMID 32960817, 2020). "This photothermal mechanism allows for the release of high concentrations of TRPV1 agonist(s) at specific tumor sites with low systemic dosages." (PMID 32545311, 2020). "Survival and correlation analyses of TRPV1 were conducted using Kaplan-Meier Plotter (KM-Plotter) and the Tumor IMmune Estimation Resource (TIMER) database." (PMID 32913462, 2020). "Further evidence shows that TRPV1 protein expression can have a protective role against tumor development." (PMID 32182937, 2020). "Tumor xenograft and peritoneal dissemination assays in nude mice were used to examine the role of TRPV1 in GC development in vivo." (PMID 33008449, 2020). "As the TRPV1 channel plays an important role in tumor cell survival, proliferation and migration, we examined the changes in TRPV1 protein levels." (PMID 32993507, 2020). "Arvanil, a synthetic TRPV1 agonist, decreases tumor weight and improves survival time in mice with implanted gliomas." (PMID 32545311, 2020). "The inhibition of tumor cell invasion triggers by CBD is probably due to high expression of TRPV1 in androgen-insensitive cells." (PMID 31991773, 2020). "The decreased expression of TRPV1 proteins in GC tissues was positively correlated with tumor size, histological grade, lymphatic metastasis, clinical stage, and was strongly correlated with poor prognosis of GC patients." (PMID 33008449, 2020). "For example, TRPV1 antagonists such as capsazepine induce apoptosis and suppress tumor growth in colorectal and oral cancer." (PMID 32604833, 2020). "As a potential tumor suppressor gene, the TRPV1 expression has been demonstrated to be regulated by exogenous stimuli or chemicals." (PMID 32913462, 2020). "This study suggests that TRPV1 served as a tumor suppressor in CRC and contributed to the development of novel therapy of CRC." (PMID 31183372, 2019). "The effects of TRPV1 expression on tumorigenesis and prognosis are different in various types of tumor." (PMID 31183372, 2019). "TRPV1 channel, known as a capsaicin receptor, was recently documented to be expressed on the cells of the immune system but also aberrantly expressed in the several tumor types." (PMID 31681615, 2019). "Several studies have demonstrated that administration of chemotherapy along with TRPV1 activator—capsaicin, results in synergistic effect leading to increased apoptosis and suppression of tumor cell migration." (PMID 31681615, 2019). "Taken together, functional TRPM8 upregulation in UM 92.1 cells suggests that TRPM8 is a potential drug target for suppressing VEGF induced increases in neovascularization and UM tumor growth since TRPM8 activation blocked VEGF transactivation of TRPV1." (PMID 30483120, 2018). "Previous studies have shown that TRPV1 acts as a tumor suppressor through inducing tumor apoptosis upon activation by its agonist." (PMID 29338036, 2018).
tumor (continued). "Studies presented here demonstrate that those tumour derived mediators directly drive sensory neuronal function (growth and sensory neuron TRPV1 activation) in a VEGF-A dependent manner." (PMID 29100335, 2017). "It has been known for a long time -even before TRPV1 channels were discovered- that lipoxygenase products, now well-known endogenous agonists of TRPV1 channels, promote tumor growth." (PMID 28640864, 2017). "The action of PAMs, such as MRS and MRS-analogs, are restricted to the site of the production of endogenous agonists of TRPV1; i.e. most probably specific to the inflammatory milieu of the proximal tumor environment." (PMID 28640864, 2017). "Agents that target the acidic pHe sensing machinery, such as ASIC1a and TRPV1 (vanilloid receptor), can prevent tumor growth." (PMID 29108231, 2017). "Other studies provide evidence that TRPV1 activation is necessary for cannabinoid-induced tumor death." (PMID 29066974, 2017). "Western blot analysis was performed using tissues of rat ipsilateral spinal cord on days 14 and 21 post-tumor cell inoculation, which expressed c-fos and TRPV1 mRNA." (PMID 26081451, 2015). "The results demonstrated that the protein expression levels of c-fos and TRPV1 in the spinal cord were significantly upregulated following tumor cell inoculation, compared with the naive and sham groups (P<0.05)." (PMID 26081451, 2015). "For example, TRPV1 expression in trigeminal ganglia neurons increases after tumor growth in the oral cavity of rats and ablation of TRPV1+ neurons reduced OSCC-induced thermal hyperalgesia." (PMID 26007300, 2015). "Lazzeri and colleagues have demonstrated that TCCs show a progressive decrease in TRPV1 protein expression as the tumor stage increases." (PMID 22523714, 2012). "This phenomenon has also been observed in a tumor pain model, and the powerful therapeutic effect of TRPV1 blockage is being explored." (PMID 23258994, 2012). "This tumor-induced release of protons is likely to activate acid sensing afferent fibers, in particular C fibers expressing TRPV1 or ASIC channels that innervate the femur." (PMID 20602757, 2010). "Furthermore, resiniferatoxin, a potent analog of capsaicin that targets TRPV1, selectively ablates sensory nerve fibers in murine models, leading to pain reduction and deceleration of tumor progression." (PMID 41601691, 2026). "This calcium circuit remodeling may underlie the decreased expression of neuropathic markers (CGRP, TRPV1, and SP) and reduced tumor invasiveness." (PMID 41576171, 2026). "Additionally, TRPV1 inhibition restored the nuclear-to-cytoplasmic (N/C) ratio—a surrogate marker for tumor aggressiveness—by approximately 70% after stretch in U-2 OS cells (p < 0.01) and fully reverted it to baseline levels in SAOS-2 cells (p < 0.05)." (PMID 41009392, 2025). "In addition, the anti-tumor potential of odorous traditional herbs that regulate TRPV1 is also discussed, hoping to develop anti-tumor drugs targeting TRPV1 receptors in the future." (PMID 40007993, 2025). "Though not yet widely translated to oncology, these technologies could be adapted to selectively ablate tumor-supportive nerves (e.g., β-adrenergic or TRPV1-positive sensory fibers) based on their molecular or anatomical signatures." (PMID 41009819, 2025). "Recent studies suggest that TRPV1 expression patterns may vary across tumor types and anatomical sites, further underscoring the need for precise, context-specific targeting." (PMID 41009819, 2025). "The neural connection between tumor and brain, together with our finding that TRPV1-expressing nociceptor neurons within this circuit become functionally altered, might contribute to these changes." (PMID 39302290, 2024). "Therefore, the regulation mechanism of the TRPM8 ion channel on TRPV1 is of great significance for the suppression of pain and tumor proliferation." (PMID 38892000, 2024).
tumor (continued). "Moreover, the inhibitory effects of TRPM8 on TRPV1 have been observed not only in pain-related studies but also in tumor studies." (PMID 38892000, 2024). "The role of TRPV1 in various inflammatory and carcinogenic pathways has been previously studied with contradictory results, revealing both pro- and anti-inflammatory and tumor-promoting and -suppressing effects." (PMID 39125864, 2024). "Furthermore, TRPV1 is aberrantly expressed in various tumor types, and differential TRPV1 expression is often associated with tumor progression and prognosis." (PMID 38734935, 2024). "Even though such a paradigm exists in various tumor cell types, where C5a plays a complex role in tumor progression and the tumor microenvironment, our results show that C5a induces rises in Ca2+ influx by interacting with TRPV1 and TRPM8." (PMID 39195219, 2024). "The remaining presence of these non-peptidergic, largely MrgD+, neurons might explain why nesting behavior in TRPV1-Cre::Floxed-DTA tumor-bearing animals is only partially restored." (PMID 39302290, 2024). "Based on our in vitro experiments showing that CAP and/or DDP exert anti-tumor effects via TRPV1 in TSCC cells, we further investigated whether they had the same inhibitory effect in vivo in a xenograft model." (PMID 39132151, 2024). "With continued exploration into TRPV1, we might witness the emergence of more tumor treatment modalities centered around this pivotal receptor in the future." (PMID 38567163, 2024). "Similarly, TRPV1 activation enhances tumor antigen presentation by dendritic cells, potentially boosting T cell-mediated immune responses." (PMID 39407657, 2024). "Furthermore, there was a noticeable increase in the expression of TRPV1 across all HNSC tumor grades." (PMID 39132151, 2024). "TRPV1 serves a dual function within the tumor microenvironment." (PMID 39407657, 2024). "Similarly, TRPV1 modulation extends to the immune system by influencing immune cell behavior in the tumor microenvironment." (PMID 39407657, 2024). "However, the upregulation of TRPV1 in colonic cancer and esophageal squamous cancer correlates with tumor progression, migration, and poor survival." (PMID 39125864, 2024). "Moreover, the antitumor efficacy of TRPV1 blockade-synergized thermotherapy against orthotopic HCT-116-Luc tumor model was further investigated." (PMID 37120615, 2023). "Moreover, TRPV1 levels are significantly increased in T-cells isolated from B16F10 tumor-bearing mice compared to control mice; this is also associated with increased basal intracellular Ca2+ levels in T-cells." (PMID 37371563, 2023). "Importantly, the TRPV1 inhibition using its specific inhibitor AMG9810 renders the tumor vulnerable to cisplatin." (PMID 37165076, 2023). "Interestingly, NANOG knockdown reduced TRPV1 expression in those tumor cells, indicating that the NANOG axis was conserved in all tested cells." (PMID 37165076, 2023). "Although indirectly, the level of TRPV1 expression within tumor tissue may estimate the content of sensory neurons." (PMID 37371563, 2023). "Although the reason for this is unclear, the differences in the tumor microenvironment, subtype of innervating SN, and the level of TRPV1 expression and activation between bone and mammary fat pad may account for this failure." (PMID 37461623, 2023). "Given the important role the TRPV1 in cisplatin-resistant phenotypes of NANOG+ tumor cells, we questioned that TRPV1 expression alone could induce these phenotypes." (PMID 37165076, 2023). "Recent studies have revealed that, in addition to transmitting and regulating nociception, TRPV1 activation may induce anti-tumor immune effects." (PMID 37025492, 2023).
tumor (continued). "Interestingly, sensory neurons innervating tumor-bearing bones maintain elevated TRPV1 expression levels even in the presence of tumor-induced injuries." (PMID 37664239, 2023). "Notably, TRPV1 blockade synergizes thermo-cytotoxicity and promotes tumor cells apoptosis via efficiently blocking Ca2+ influx." (PMID 37120615, 2023). "Thus, TRPV1 blockade-synergized thermo-immunotherapy effectively triggers the immune responses through the infiltration of tumor-attacking immune cells in PDAC model." (PMID 37120615, 2023). "TRPV1 activation and/or blockade may have markedly different effects on carcinogenesis depending on both the tumor and its microenvironment." (PMID 37371563, 2023). "Thus, our results indicate that TRPV1 by itself was sufficient to induce the cisplatin resistance of tumor cells via EGF-EGFR signaling pathway." (PMID 37165076, 2023). "Thus, TRPV1 blockade plays an important role in suppressing MDSCs through the aPD-L1 infiltration and TGFβ1 modulation in tumor." (PMID 37120615, 2023). "Thus, TRPV1 blockade-mediated suppression of HSF1 nuclear translocation is a key process in alleviating tumor matrix in PDAC models." (PMID 37120615, 2023). "Many studies indicated TRPV1 as a tumor suppressor of CRC; therefore, its activation may be feasible for this neoplasm." (PMID 37507867, 2023). "Here, we found that the TRPV1 is overexpressed by NANOG in cisplatin-resistant tumor cells and mediates Ca2+ influx and subsequent increases in autophagic EGF secretion, which activates the EGFR-AKT signaling pathway consequently contributing to cisplatin resistance." (PMID 37165076, 2023). "The effect of TRPV1 activation in immune cells on tumor growth and metastasis might be different from that of neuronal TRPV1." (PMID 37371563, 2023). "The mice bearing A549-WT tumor and A549-TRPV1 KD tumor in the PBS groups exhibited similar tumor growth profiles with ~15.0-fold increases during 30 days, demonstrating that TRPV1 channel itself has no influence on tumor growth under non-hyperthermia conditions." (PMID 37120615, 2023). "Notably, the strategy of TRPV1 blockade shows a distinct advantage in the eradication of the tumor cells surviving from hyperthermia upon irradiating IS-Micelles at tumor." (PMID 37120615, 2023). "TRPV1 may be involved in the occurrence of cervical squamous cell carcinoma by regulating macrophage infiltration and tumor immune escape.Currently, tumor immune escape is a hot topic in the field of tumor." (PMID 37404813, 2023). "We further demonstrated whether TRPV1 blockade-synergized thermo-immunotherapy arouses long-term memory effect to prevent tumor recurrence." (PMID 37120615, 2023). "Interestingly, IS-Micelles distinctly delayed the tumor growth upon irradiation via TRPV1 blockade-synergized thermotherapy." (PMID 37120615, 2023). "Thus, we applied the immunofluorescence staining to assess the role of TRPV1 blockade in interfering the intranuclear HSF1 translocation and intracellular HSP70 expression in tumor cells under hyperthermia caused by CuS-NCs." (PMID 37120615, 2023). "The results suggest that TRPV1 is involved in the process of tumor immune regulation in CSCC." (PMID 36072430, 2022). "The results of xenograft mouse model through MCF-7 by Kim and colleagues have shown that tramadol may have receptor-specific anti-tumor effects through ER, PR and TRPV1." (PMID 35155248, 2022). "On the other hand, TRPV1 deficiency did not alter paw volume or weight, indicating no significant alteration in tumor growth." (PMID 36138983, 2022). "In accordance with the demonstration that a mild temperature upregulates the expression of PD-L1 in tumor cells, in TRPV1-positive BC cells, the TRPV1 antagonist CPZ completely reverts the CPS-induced increase in PD-L1, supporting the role of TRPV1 in PD-L1 regulation." (PMID 35681623, 2022). "Whether TRPV1 is an important factor in macrophage depolarization mediation, and tumor microenvironment remodeler requires in‐depth study." (PMID 35620019, 2022).